REST (RE1 silencing transcription factor)
Diseases named in the same sentence as REST in open-access papers (continued):
Sharing a sentence is not in itself a finding about the gene and the disease.
cancer (continued). "This is not unexpected, given the frequent loss of REST protein by ubiquitin mediated proteolysis in various cancers." (PMID 35177031, 2022). "Analysis of the various cancers revealed that several putative REST target genes, including Polo Like Kinase 1 (PLK1), ADAM Metallopeptidase Domain 12 (ADAM12), Troponin T1 (TNNT1), and cell migration-inducing and hyaluronan-binding protein (CEMIP, KIAA1199) were highly dysregulated." (PMID 35177031, 2022). "Furthermore, TUBB3/βIII-tubulin expression can be independently induced upon REST siRNA treatment in cancer cells." (PMID 35573698, 2022). "REST is ranked highly among many cancer’s BART results for down-regulated genes." (PMID 33778495, 2021). "However, the functional implications of REST and its requirement for HDACi‐induced anti‐cancer effects are not well understood." (PMID 32720471, 2020). "REST had been reported as a master regulator in cancer development." (PMID 31964418, 2020). "Inhibition of either REST or the enzyme decreased cancer aggressiveness." (PMID 31905747, 2019). "To further understand how DEGs were regulated, we analysed transcription factor (TF) binding using Enrichr and observed that DEGs were enriched for targets of TFs associated with self-renewal and cancer stem cell function (SUZ12, SOX2, REST, EZH2, SMAD4 and NANOG)." (PMID 31014368, 2019). "Interestingly, the role in cancers is relevant also for therapeutic perspectives affecting the REST cooperations." (PMID 31905747, 2019). "Moreover, several transcriptional factors, such as NF-κB, c-myc and β-catenin, can activate LIN28 and repress let-7 expression to augment cancer progression, while REST and ESE3/EHF are transcriptional repressors of LIN28." (PMID 30016974, 2018). "REST expression can be abnormally regulated in cancer cells." (PMID 27289382, 2016). "REST was highly expressed in EC cell lines, but decreasing REST gene expression increased proliferation (FC: 1.13X, p < 0.0001), migration (1.72X, p < 0.0001), and invasion (FC: 7.77X, p < 0.05) in Ishikawa cells, which are hallmarks of cancer progression and metastasis." (PMID 39273639, 2024). "Additionally, further REST diminution in HeLa cells by means of siRNA treatment altered the expression of neuronal target genes containing the RE1 sequence, suggesting a potential role for REST in the alteration of many neural genes in cancer with potential application in diagnosis." (PMID 36984538, 2023). "Interestingly, REST showed diverse role in the progression of these cancers." (PMID 31041193, 2019). "As REST controls many cellular processes fundamental to normal physiology and disease aetiology, ∆E3 manipulation may have a broad range of clinical implications (e.g. cancer therapy and stem cell engineering)." (PMID 28524599, 2017). "Thus, the downregulation of REST, which is seen in actively proliferating cancer cells, might be involved in the regulation of mGluR1 and in cellular transformation during KSHV induced cancer development." (PMID 25299066, 2014). "REST function was also studied in these cells, by observing the effects of gene silencing on: (I) HAR1A expression; (II) cancer cell proliferation, apoptosis, migration; (III) expression of neural differentiation genes." (PMID 39602392, 2024). "REST (RE1 silencing transcription factor) and RB1 expressions are both downregulated by Interleukin 6 in cancer cells." (PMID 39480826, 2024). "The SUZ12, REST, and EZH2 genes were reported to contribute to the stemness of cancer cells, and they exhibited higher expression levels in the higher NAS group." (PMID 36309750, 2022). "REST target genes upregulated in ER- or TNBCs include MYC, LIF, and EGFR which play significant roles in cancer progression, cell proliferation and endocrine resistance." (PMID 35177031, 2022). "The hub genes (PIK3CA, STRN, C9orf102, REST, and NHLRC2) obtained from LinkedOmics were submitted to GSCALite for cancer pathway activity and drug sensitivity analysis." (PMID 34367282, 2021).
cancer (continued). "Five TFs, SUZ12, SMAD4, REST, EZH2 and NFE2L2, were found to be enriched in all four cancers, suggesting that transcriptional dysregulation of tumors with aberrant AMPK signaling involved direct physical associations of these TFs with target DEGs." (PMID 32807122, 2020). "HOTAIR is deregulated in various cancers and can serve as a scaffolding to facilitate the recruitment of the PRC2 and LSD1/CoREST/REST complexes." (PMID 33291485, 2020). "Here, we report the increased expression of AP-1, ATF2, REST, and EGR3, all transcription factors involved in cancer cell invasive behavior." (PMID 30813636, 2019). "In this work we have shown that REST reduces HIF-1α expression and glycolysis in hypoxia, two promising targets for cancer therapy." (PMID 26647819, 2015). "By interacting with REST and other cofactors, RCOR1 modulates chromatin structure to inhibit gene transcription, playing a vital role in processes such as neurodevelopment, cellular differentiation, and cancer progression." (PMID 40209953, 2025). "Having identified the subcellular localization of the lncRNAs in the cell, we then investigated whether REST silencing and HAR1A overexpression affect the cell proliferation and apoptosis of cancer cells." (PMID 39602392, 2024). "In non-nerve cells and tumors (such as lung, breast and colon), REST plays an anti-cancer role, but its research in GBC has not been reported." (PMID 37821907, 2023). "Moreover, we also conducted cancer pathway activity and drug sensitivity analysis of hub genes (PIK3CA, STRN, C9orf102, REST, and NHLRC2) obtained from LinkedOmics." (PMID 34367282, 2021). "It was found that REST expression was not critically required for Daoy proliferation or HDACi‐induced anti‐proliferation effects, suggesting that the HDACi anti‐cancer mechanism is independent of REST expression in the Daoy cells." (PMID 32720471, 2020). "We found that REST cistromes were distinct among cell types, with REST binding to several tumor suppressors specifically in cancer cells, whereas 7% of the REST peaks in non-neuronal cells were ubiquitously called and <25% were identified for ≥5 cell types." (PMID 24922058, 2014). "In addition, KCNK15‐AS1 upregulation recruits MDM2 to activate phosphatase and tensin homolog (PTEN) transcription by promoting the ubiquitination of RE1 silencing transcription factor (REST), and PTEN expression suppresses the AKT pathway and inhibits cancer progression." (PMID 40448344, 2025). "The role of REST has not yet inspected in another well-known herpes virus, Epstein–Barr virus (EBV), which is known to exhibit both latent and lytic life cycles, associated with several human cancers, and potentially in various autoimmune disorders." (PMID 40006989, 2025). "Regarding another context, the role of REST regulation in cancer is not fully elucidated." (PMID 37301955, 2023). "The most well-known lncRNA is HOTAIR, a oncogene in human cancer, its 5ʹ domain could bind polycomb repressive complex 2, while its 3ʹ domain bound the LSD1/CoREST/REST complex, thereby controlling target gene expression via specifying the pattern of histone modifications." (PMID 34699314, 2021). "This may indicate that these inhibitors do not entirely depend on the REST recruited HDACs and they possibly arrest cancer growth through other HDACs complexes and/or non‐histone protein yet, it requires further investigation." (PMID 32720471, 2020). "This suggests that CTCF, and most likely RAD21 and other factors such as REST, are driving the arrangement of nucleosomes and perhaps dictating DNA methylation patterns, offering a potential explanation for the substantial reorganization of NDRs to primarily overlap CTCF in the cancer cells." (PMID 24916973, 2014). "PRC2 and LSD1/CoREST/REST complex play important roles in the epigenetic regulation of gene expression, it is not surprising that HOTAIR is deregulated so many types of cancer." (PMID 26658322, 2015).
cancer (continued). "In contrast, REST mRNA was induced in CORL47 cells but not in THP1 cells, suggesting that REST upregulation tracks with the neuroendocrine SCLC lineage, but not with ORY-1001 sensitivity across cancer cell lines." (PMID 36008402, 2022).
neurodegenerative disease (24 papers, 2009 to 2025). A disorder of the central nervous system characterized by gradual and progressive loss of neural tissue and neurologic function. "The repressor element 1-silencing transcription factor (REST) has recently been associated with mediating cell death in neurodegenerative diseases." (PMID 35418568, 2022). "REST is considered as a master transcriptional regulator of neuron-specific genes and dysregulation of REST has been implicated in a number of neurodegenerative diseases." (PMID 34215255, 2021). "Dysregulation of the REST complex has been implicated in neurodegenerative disease including Alzheimer’s Disease26." (PMID 33742053, 2021). "Using specific ASOs and a cellular model of HD, our present study validates mechanism by which a common splicing (∆E3) modulates REST activity, as well as its potential as a therapeutic target for HD—a neurodegenerative disease associated with excessive nuclear REST." (PMID 28524599, 2017). "Taken together, the depletion of REST from nucleus may be a universal feature in prion and associated neurodegenerative diseases." (PMID 28515679, 2017). "Additionally, far more than above functions, REST has also been implicated in the pathogenesis and proposed as a therapeutic target of neurodegenerative diseases." (PMID 26919115, 2016). "Our findings underscore dopaminergic REST's essential role in maintaining a regulatory network for neuroprotection against Mn toxicity and potentially other neurodegenerative diseases." (PMID 39178947, 2024). "Overall, the transcription factor REST is a promising therapeutic target in AD and other neurodegenerative diseases." (PMID 33185010, 2021). "Given the wide variety of neuron‐specific REST gene targets, it has recently gained recognition as a modulator of neuronal homeostasis in both healthy brain ageing and neurodegenerative disease contexts." (PMID 33185010, 2021). "Repressor element 1-silencing transcription factor (REST) exerts protective effects in many neurodegenerative diseases." (PMID 34756885, 2021). "Initial data about neurodegenerative diseases were reported several years ago when reviews about the mechanisms of REST and its dependent therapies were first proposed." (PMID 31905747, 2019). "The RE1-silencing transcription factor (REST) was recently shown to be neuroprotective and aberrantly associated with protein aggregates during the course of neurodegenerative diseases." (PMID 29037228, 2017). "In neurodegenerative diseases, REST has often been observed within cytoplasmatic autophagosomes, and its levels show no increase in the nuclei of hippocampal neurons." (PMID 28842657, 2017). "miR-29a regulates neurogenic markers through targeting REST in mesenchymal stem cells, which provides advances in neuronal differentiation research and stem cell therapy for neurodegenerative diseases." (PMID 24841827, 2014). "The functional relevance of SIRT6 depletion in the aging brain and neurodegenerative diseases could influence the capacity of REST to protect the brain from neurodegeneration." (PMID 39511137, 2024). "Collectively, these studies suggest that targeting REST may be a possible therapeutic route for neurodegenerative diseases, including ALS." (PMID 34281203, 2021). "However, when neurodegenerative diseases occur, the mechanism looks different; REST levels decrease." (PMID 31361762, 2019). "Since REST exerts protective effects in neurodegenerative disorders such as AD and PD, it may have broad protective mechanisms and be a highly relevant molecular target for developing therapeutics for neurodegenerative diseases." (PMID 39178947, 2024). "Therefore, if nuclear translocation of REST is indeed protective in healthy ageing cortical neurons, then failure of neurons to upregulate nuclear REST in TgF344‐AD rats could be equally detrimental in the context of neurodegenerative disease." (PMID 33185010, 2021).
neurodegenerative disease (continued). "The development of neurodegenerative diseases may thus be favored by the expression of genes and processes related to neuronal degeneration, which, in the brains of healthy, aging humans, may be repressed by REST." (PMID 26465007, 2015).
neurological diseases (23 papers, 2012 to 2025). "Re-expression or overexpression of REST in some mature neurons has been linked to many diverse types of neurological diseases." (PMID 40427470, 2025). "The dysregulation of REST has also been implicated in several neurological diseases, including Alzheimer’s disease, suggesting that Scp1 dysfunction is associated with these diseases." (PMID 38612548, 2024). "Our data reveals three connections between the REST gene and the risk of acquiring neurological diseases." (PMID 37518996, 2023). "Our data indicate that REST has a protective role in physiological aging by regulating the autophagic flux and the senescence program in neurons, with implications for neurological disorders associated with aging." (PMID 34520100, 2021). "Of note interfering with REST levels leads to altered NSCs differentiation and aberrant REST function has been associated with neurological disorders." (PMID 22701651, 2012). "This indicates that astrocytic REST could be a potential molecular target for the treatment of Mn toxicity and other neurological disorders associated with EAAT2 dysregulation." (PMID 34756885, 2021). "Re-expression of REST in mature neurons has been identified in some neurological diseases." (PMID 40427470, 2025). "Finally, network-based integrative analysis of GWAS of RE1s reveals possible neurological disorders and probable REST-targeting genes." (PMID 37518996, 2023). "The expression and activity of REST are altered in a number of neurological diseases; depending on the tissue and the specific pathology, REST acts under some circumstances as a protective factor and under other conditions as a promoter of insult-induced neuronal death or dysfunction." (PMID 33589593, 2021). "These indicate that astrocytic REST could be a critical molecular target for developing novel neurotherapeutics against excitotoxic neuronal injury, which is also inherent to many other neurological disorders." (PMID 34756885, 2021). "While no research evidence to demonstrate that REST regulates the JAK–STAT signaling pathway directly, a potential link between REST and JAK–STAT can be seen in several neurological disorders." (PMID 37373133, 2023). "In several pathophysiological processes, such as neurogenesis, neurological disorders, and non-neuronal tumorigenesis, the dynamic balance between REST 4 and NRSF has been reported as playing an important role." (PMID 35300407, 2022).
infection (12 papers, 2007 to 2025). The state of being infected such as from the introduction of a foreign agent such as serum, vaccine, antigenic substance or organism. "Thus, the authors predicted that the REST/CoREST/HDACs complex could cause HSV-1 gene silencing at low multiplicities of infection (MOI)." (PMID 17555596, 2007). "The fundamental findings summarized above indicate that the CoREST/REST complex is involved in the suppression of viral gene expression, in both productive infection and in the establishment of latent, silent infections in sensory neurons." (PMID 23628827, 2013). "REST is implicated in various roles in latency establishment, negative gene regulation of viral genes on infection as well as in aiding protection of the host from infection." (PMID 40006989, 2025). "This suggests that REST exerts a repressive effect on the viral genome through association with repressors other than histone deacetylases, although, in this study, expression of the LAT and viral miRNA was reduced following infection with the wild-type REST virus." (PMID 34452335, 2021). "The expression of REST was significantly decreased after siRNA infection." (PMID 24841827, 2014). "Late in infection at least a fraction of HDAC1, CoREST, LSD1 and REST were exported into the cytoplasm." (PMID 23628827, 2013). "REST, a transcriptional repressor that limits neuronal gene expression in non-neuronal tissues, was suppressed during 2.2 infection but not 2.3." (PMID 36926515, 2023). "We found that infection of SARS-CoV-2 could elevate the expression of Tnfα and Il-6, and downregulate the expression of Glut1, and these effects were blocked by the knockdown of REST." (PMID 34916489, 2021).
brain diseases (7 papers, 2015 to 2023). "In addition to physiological processes, REST governs also events dependent on processes, such as metabolic alterations, for example, obesity and insulin resistance, up to frank brain diseases, where the factor plays pathogenic roles." (PMID 31905747, 2019). "Therefore, we investigated whether genes implicated in brain disorders are more likely to be targeted by REST specifically in humans." (PMID 25990720, 2015). "Of note, several REST inhibitors, including valproic acid and X5050, have been shown to be clinically effective in rescuing many brain diseases such as seizures." (PMID 37288660, 2023). "New effects induced in neurons during brain diseases depend on the localization of REST, in the nucleus, where functions and toxicity occur, and in the cytoplasm." (PMID 31905747, 2019). "Rather, the following sections will summarize the present knowledge of the role of REST in several brain diseases as well as in terms of therapy." (PMID 26465007, 2015). "All of brain disorder gene sets except ID genes were enriched with REST binding relative to all human genes – probably due to the enrichment of neural genes in REST targets." (PMID 25990720, 2015). "The enrichment of genes for learning and memory functions among the human-specific REST-bound genes prompted us to study whether those genes with human-specific binding are related to brain disorders." (PMID 25990720, 2015). "During the last 15 years, growing interest in the role of REST in adult neurons has paved the way to the identification of multiple, highly interesting processes that take place in the physiology and pathology of the brain as well as in several brain diseases." (PMID 26465007, 2015). "In addition, at least some of these genes could be involved also in the pathogenesis of various brain diseases recently shown to depend on REST for numerous, interesting aspects." (PMID 26617488, 2015). "In light of the key role of REST in brain development and function, it is not surprising that it also plays mechanistic roles in the pathogenesis of several brain diseases." (PMID 26465007, 2015).
adenocarcinoma (6 papers, 2021 to 2024). A common cancer characterized by the presence of malignant glandular cells. "Silencing REST in C4-2 (NE-/AR+) adenocarcinoma cells leads to induction of NE markers." (PMID 38777812, 2024). "Upon examining the Beltran_NM2016 RNA-seq dataset, we found that REST is significantly lower, while NE markers are significantly higher, in 15 NEPC samples compared to 34 CRPC-adenocarcinoma samples (P = 1.05E-06)." (PMID 38777812, 2024). "Furthermore, HP1α ectopic expression in adenocarcinoma cells subjected to ADT promoted NE transdifferentiation in a mechanism that involves transcriptional repression on the promotors of AR and REST." (PMID 39682746, 2024).